EPO (erythropoietin)
Diseases named in the same sentence as EPO in open-access papers (continued):
Sharing a sentence is not in itself a finding about the gene and the disease.
anemia (continued). "CMV infection has been reported to inhibit erythropoietin production, which induces or exacerbates anemia in patients." (PMID 34442018, 2021). "In general, patients with HS have increased reticulocyte counts and elevated EPO levels, to compensate for anemia." (PMID 33672223, 2021). "The current guidelines on anemia management of CKD mainly focus on the provision of recombinant human erythropoietin (EPO) and its analogs, known as erythropoiesis-stimulating agents (ESAs), along with iron supplementation." (PMID 35115942, 2021). "Erythropoietin and interleukin 1 beta (IL-1β), which are increased in condition of anemia and inflammation respectively, are two potent inducers of Fgf23 at the transcriptional level." (PMID 34149625, 2021). "With advancing renal impairment, erythropoietin production decreases progressively and serves as the foremost reason for anemia in uremic patients." (PMID 34828498, 2021). "Despite these in-advantage factors in the EPO group (older age with more co-existing conditions and anemia with inadequate blood transfusion), there was a better survival rate in the EPO group." (PMID 34831360, 2021). "The current guidelines on the management of anemia in CKD mainly focus on erythropoietin-stimulating agent (ESA) therapy, iron therapy, and blood transfusion." (PMID 34276361, 2021). "Recombinant human EPO (rHuEPO) is administered clinically for the treatment of anemia that is secondary to chronic kidney disease, or for certain hematological malignancies." (PMID 35008482, 2021). "The correction of anemia has been shown to increase libido, sexual desire, and improve erectile function, and EPO therapy has been shown to improve erection quality in HD patients." (PMID 33918412, 2021). "First, reduced EPO production that is too low to counteract anemia and a blunted response of erythroid progenitors to EPO represent essential underlying mechanisms." (PMID 34250431, 2021). "FG-4592 is currently used for the clinical treatment of CKD anemia by promoting endogenous EPO synthesis." (PMID 34403364, 2021). "The reason for the observed outcome was heterogeneity of anemia in HF patients and a large proportion of HF patients already have high EPO levels, with resistance of bone marrow to its action." (PMID 34453627, 2021). "With age, anemia becomes more prevalent due to poor hematopoietic function or weakened response to erythropoietin." (PMID 34208273, 2021). "Recently, a PHD inhibitor called roxadustat (FG-4592) was approved to treat anaemia by increasing EPO production." (PMID 34251509, 2021). "Before the introduction of recombinant human erythropoietin, AASs were used in the treatment of anemias, indeed, AASs are capable of increasing erythropoietin secretion." (PMID 33477800, 2021). "Given its beneficial effects, erythropoietin is produced by recombinant deoxyribonucleic acid (DNA) technology, and this recombinant human erythropoietin (rhEPO) and its newer analogues are now therapeutically used for the treatment of anemia." (PMID 33628672, 2021). "Hematologic alterations are often seen in ESRD patients under dialysis and a common complication is anemia, which is explained by reduced production of erythropoietin, a renal hormone essential to the production of hemoglobin." (PMID 34574503, 2021). "Since the landmark study of the use of erythropoietin in 1987, the cornerstone of anemia treatment in CKD has been erythropoiesis-stimulating agent (ESA) therapy." (PMID 34136787, 2021). "Adult haplotype A sheep can switch from the synthesis of Hb-A (α2β2A) to the juvenile haemoglobin C (Hb-C; α2β2C) in response to hypoxia, anaemia or erythropoietin injection." (PMID 34680955, 2021). "Clinically guided appropriate pre-operative use of intravenous or oral iron, vitamin B12, folic acid or erythropoietin for patients suffering from anaemia and/or low iron stores should be implemented in patients undergoing moderate and major spinal surgery." (PMID 33691620, 2021).
anemia (continued). "Erythropoietin levels are increased in proportion to HF severity but are lower than expected for the degree of anemia, suggesting blunted erythropoietin production." (PMID 33540753, 2021). "The current study provides primary evidence regarding the need for simultaneous regulation of hepcidin and EPO to enhance the efficacy of IV iron supplementation for the treatment of anemia under chronic inflammatory conditions." (PMID 34873429, 2021). "Historically, the search for EPO began as early as 1875, when anemia-like symptoms were diagnosed in patients living at low altitude and characterized by low blood oxygen levels." (PMID 34440909, 2021). "We were intrigued by these findings as increased plasma FGF23 and EPO levels are often observed in anemia." (PMID 34362888, 2021). "Instead, the kra monkey BM responded appropriately when EPO was elevated in the plasma, comparable to data shown recently for four kra monkeys infected with P. coatneyi-infected RBCs and monitored for anaemia." (PMID 34969401, 2021). "Erythropoietin (EPO) has been considered to improve patients’ anemia state, but its efficiency and safety remains controversial." (PMID 33213494, 2020). "HIF stabilizers act by restoring EPO levels and reducing hepcidin and have been used effectively to enhance hemoglobin levels in patients suffering from anemias, including CKD patients." (PMID 33143240, 2020). "One clinical study showed that the EPO level in patients with CKD anemia was generally normal or slightly elevated, which was consistent with our experimental results." (PMID 33178327, 2020). "Roxadustat is a new type of drug for the treatment of anaemia, and it can stimulate endogenous EPO within or near the physiologic range and increase haemoglobin levels." (PMID 32856389, 2020). "The other purpose of this study is to reconfirm the efficacy of rHu-EPO subcutaneous administration on improving patients’ anemia state." (PMID 33213494, 2020). "All patients had at least one individual risk-factor (91%), including co-morbidity (such as diabetes and COPD, chronic obstructive pulmonary disease, 75%) and anemia requiring supportive care with EPO (67%)." (PMID 32899553, 2020). "An inadequate erythropoietin feedback mechanism is suspected to be a major contributor in HIV-related anaemia." (PMID 32571345, 2020). "The intended major field of application is to study treatment effects such as chemotherapy induced anaemia or stabilizing haemoglobin levels in CKD patients by EPO- and iron applications." (PMID 32451387, 2020). "Patients undergoing hemodialysis therapy have high blood hepcidin levels due to various factors such as chronic inflammation and infection, which contributes to the anemia refractory to EPO." (PMID 32069878, 2020). "Due to EPO’s effects on the production of red blood cells, it has been used clinically since 1990 to treat anemia of prematurity." (PMID 32098276, 2020). "One of these promising neuroprotective candidates is Erythropoietin (Epo), an endogenous hormone, which in its recombinant form has been used for the prevention of anemia of prematurity for almost three decades." (PMID 32903382, 2020). "The understanding of the impact of inflammatory cytokines on erythropoietin production and hepcidin synthesis will enable to unravel the net of interactions of multiple factors involved in the pathogenesis of the anemia of chronic disease." (PMID 31979104, 2020). "The reduction in anemia prevalence at high altitudes is most likely due to the effects of hypoxia on stimulating the production and release of erythropoietin (EPO), the most potent stimulator of erythropoiesis, in renal and extra-renal tissues." (PMID 31940318, 2020). "Recombinant human erythropoietin (rhEPO) is routinely used to prevent anemia in preterm infants; however, the effect of rhEPO on ROP development is still controversial." (PMID 33076939, 2020).
anemia (continued). "Nine meta-analyses studied interventions for anemia in CKD, of which only meta-regression analyses of RCTs achieved statistical significance, which shows that a higher dose of erythropoietin stimulating agents was associated with higher mortality." (PMID 32024136, 2020). "Treatment options in case of severe anaemia comprise erythrocyte transfusion, EPO application and iron supplementation." (PMID 32451387, 2020). "Of note is that treatment with EPO alone yielded promising neurological outcomes in preterm infants treated for anemia at 27–30 weeks-of gestation and after neonatal HIE at term." (PMID 32098276, 2020). "In spite of this, HR values for cumulative mortality were higher for EPO than for anemia (HR 4.05, 95% CI 2.29–7.16, p < 0.001 for logEPO vs. HR 2.40, 95% CI 1.51–3.80, p < 0.001 for hemoglobin)." (PMID 33330669, 2020). "Current treatments for anemia in CKD mainly require recombinant human erythropoietin (rhEPO) or its analogs (erythropoiesis stimulating agents [ESAs]) and iron supplementation (intravenous and/or oral)." (PMID 33597868, 2020). "The causes of anemia in CKD patients are multi-factorial, including deficiency in erythropoietin (EPO), reduced iron availability, and inflammation." (PMID 33597868, 2020). "Hydroxyurea was frequently used to control splenomegaly and, especially, white blood cell count, whereas erythropoietin, danazol, and vitamin supplements are often used with the aim of mitigating anemia." (PMID 31832751, 2020). "Because EPOR was expressed by TAMs and anemia can induce EPO secretion, which can activate the EPO-EPOR signal to promote the protumor functions of CD163+EPOR+ TAMs." (PMID 32908942, 2020). "Erythropoietin (Epo) should be considered as second line treatment for IBD patients with severe or symptomatic anaemia refractory to IV iron." (PMID 33198376, 2020). "In patients with anemia, observed EPO levels were lower than expected in 73% of patients, whereas 12% of patients had higher than expected levels of EPO." (PMID 33330669, 2020). "The impact of anemia treatment with erythropoietin stimulating agents (ESA) on health-related quality of life (HRQOL) in chronic kidney disease (CKD) patients is controversial, particularly regarding optimal hemoglobin (Hb) target ranges." (PMID 32641153, 2020). "Previous reports showed that the value of serum EPO in patients with renal insufficiency was less than the upper limit despite the presence of anemia." (PMID 32311841, 2020). "During severe stress (like anemia or hypoxia) kidney peritubular cells heighten EPO concentrations to as high as 10 IU/mL." (PMID 33255601, 2020). "Current guidelines and recommendations for anemia management in patient with CKD is recombinant human erythropoietin (rhEPO) and its analogs (called erythropoiesis-stimulating agents, ESAs), supplemented with intravenous iron administration." (PMID 32869703, 2020). "Erythropoietin (EPO) is a 30.4-kDa glycoprotein hormone produced primarily by the kidneys that regulates red blood cell production in response to anemia." (PMID 32993806, 2020). "Factors that negatively regulate exercise-related HAMP levels include anemia, hypoxia that triggers erythropoietin (EPO) secretion, and hemolysis." (PMID 32599787, 2020). "A previous study reported showed that 12 patients who underwent PD showed improved erythropoietin-resistant anemia by carnitine supplementation." (PMID 32003308, 2020). "Carnitine deficiency contributes to developing various pathological conditions, such as cardiac dysfunction, muscle weakness, and erythropoietin-resistant anemia in patients undergoing hemodialysis." (PMID 32003308, 2020). "The prolyl hydroxylase inhibitors (PHIs), which act by stabilizing HIFα to stimulate endogenous EPO production, are promising new agents for treating anemia of chronic kidney disease and perhaps other etiologies." (PMID 32983414, 2020).
anemia (continued). "Since the combination of EPO-stimulating and iron agents is an important anemia management strategy for patients undergoing hemodialysis, acai has potential applications in therapy for various types of anemia." (PMID 32092924, 2020). "Out of 563 patients with severe aortic stenosis undergoing TAVR at our center over the study period, a complete baseline profile including anemia status, iron status, and EPO levels was available in 407 patients." (PMID 33330669, 2020). "EPO is also recommended by the European Medicinal Agency to reduce the need for blood transfusions in adults with moderate anaemia who are about to undergo major orthopaedic (bone) surgery, such as hip surgery." (PMID 31468111, 2020). "A 26-year-old man with anaemia related to renal failure, who was administered recombinant human EPO subcutaneously, developed anti-EPO antibody-mediated PRCA." (PMID 32856389, 2020). "Sato and coworkers recently showed that, in CKD related anemia, there is a disruption of the mechanism linking hypoxia with the consequent EPO induction." (PMID 32708735, 2020). "Understanding erythropoiesis and its relationship with EPO and iron, leads to understand in part the pathophysiologic processes of anemia consecutive to CKD." (PMID 32899941, 2020). "Erythropoietin (EPO), which is clinically used for anemia, reportedly exerts pleiotropic effects in ALI." (PMID 32265704, 2020). "A large proportion of end-stage renal disease (ESRD) patients under long-term haemodialysis, have persistent anaemia and require high doses of recombinant human erythropoietin (rhEPO)." (PMID 32994444, 2020). "In conclusion, GABA shows a new physiological role in EPO production, and it can thus can contribute to the prevention of anemia when used alone or in combination with other anemia treating drugs." (PMID 32290638, 2020). "Recombinant human EPO (rHuEPO) is used in clinical practice for the treatment of several types of anemia." (PMID 32471308, 2020). "The understanding of the impact of inflammatory cytokines on erythropoietin production and hepcidin synthesis will enable one to unravel the net of interactions of multiple factors involved in the pathogenesis of the anemia of chronic disease." (PMID 31979104, 2020). "Secondary hyperparathyroidism, which is frequently observed in CKD, contributes to the development of anemia and greater resistance to erythropoietin." (PMID 31979104, 2020). "The application of erythropoiesis-stimulating agents (ESAs) such as recombinant human erythropoietin (rHuEPO) has dramatically improved the management of anemia in MHD patients." (PMID 33293895, 2020). "Erythropoietin demand reflects the need for erythropoietin (including endogenous and exogenous EPO) in ESRD patients in order to produce sufficient Hb to eliminate anemia." (PMID 32318578, 2020). "Second, tissue hypoxia due to low cardiac output, hypotension, or anaemia leads to increased endogenous erythropoietin production and enhanced iron availability." (PMID 32993543, 2020). "Erythropoietin (EPO) regulates red blood cell production, and recombinant EPO is used primarily to treat anemia in chronic kidney disease." (PMID 33330462, 2020). "Erythropoietin (produced by the kidney) and iron (provided from recycled senescent red cells) deficiencies are the main reasons that contribute to CKD-associated anemia." (PMID 32899941, 2020). "Currently, FG-4592 is used to improve the anemia of CKD patients since it can enhance the erythropoietin (EPO), a downstream gene of HIF." (PMID 32051732, 2020). "In this regard, serum EPO levels can be used to predict renal reversibility in patients with MM if they have concurrent anemia." (PMID 32311841, 2020). "Overexpression of inflammatory cytokines, leading to a shortened survival of red blood cells, suppression of erythroid progenitor cells, impaired iron utilization, and inadequate erythropoietin production, majorly contribute to anemia in cancer." (PMID 32782887, 2020).
anemia (continued). "One of the main TCM uses of Radix Paeoniae Alba is to treat blood deficiency, and an in vivo investigation has demonstrated that Radix Paeoniae Alba extract increased haemoglobin, haematocrit and serum erythropoietin in anaemia-induced rats." (PMID 33187543, 2020). "Erythropoietin (EPO) is one of the erythropoiesis-stimulating drugs, which promotes hematopoietic stem cells differentiate into red blood cell to improve the anemia state of patients." (PMID 33213494, 2020). "This hormone, subsequently named erythropoietin (EPO), is now known to regulate the formation of red blood cells by stimulating bone marrow, and is widely used for the clinical treatment of anemia caused by various factors." (PMID 32154256, 2020). "Secondly, since the renal function is compromised, the kidneys decrease or cease the production of erythropoietin which leads to anemia or low Hb in ESRD patients." (PMID 32569265, 2020). "Anemia is also a common manifestation with renal insufficiency, and renal dysfunction leads to decreased erythropoietin secretion and anemia." (PMID 32727495, 2020). "For example, erythropoietin (EPO) is used to treat anemia, granulocyte colony-stimulating factor (G-CSF) against neutropenia, and granulocyte-macrophage colony-stimulating factor (GM-CSF) to treat neutropenia and fungal infections." (PMID 33050544, 2020). "Collectively, our data using two distinct therapeutic agents, namely EPO and FG‐4592, showed that both extended and acute reversal of anemia‐related manifestations in a model of CKD, respectively, were associated with a marked lowering of iFGF23." (PMID 32476270, 2020). "Our analysis is the first to show that EPO > 25 mIU/mL is an independent positive predictive factor for the achievement of a major renal response in patients with concurrent RI and anemia." (PMID 32311841, 2020). "CKD patients suffer from reduced erythropoietin (EPO) levels, and it has been shown that besides causing anemia, EPO reduction had direct effects on the cardiovascular system of these patients." (PMID 32150864, 2020). "To determine renal anemia treatment patterns, we automatically collected information on the practice of anemia treatment patterns such as erythropoietin stimulating agent (ESA) doses and administration frequencies, and targeted hemoglobin maintenance rate." (PMID 31914095, 2020). "In situations where erythropoietin demand and/or hypoxia are present (as in severe anaemia), hepcidin levels are decreased." (PMID 32107492, 2020). "In patients with ESRD, anemia is a common clinical problem because of the decreased production of erythropoietin and multiple comorbidities inducing the decrease in red blood cell production, such as iron deficiency or systemic inflammation." (PMID 32213981, 2020). "A specific treatment for anemia was used in 99 patients (36.6%) (transfusions, erythropoietin, iron, vitamin B12 and/or folic acid)." (PMID 32235484, 2020). "Fourthly, EPO is synthetized by the kidney not only as a response to anemia or hypoxia, but also when stimulated by reduced renal perfusion caused by low cardiac output." (PMID 33330669, 2020). "As serum EPO levels are physiologically regulated by the degree of hemoglobin concentration, the presence of anemia is necessary for inducing an increase in EPO production." (PMID 32311841, 2020). "Anemia has a multifactorial origin related to the inflammatory chronic disease, reduced erythropoietin synthesis due to renal failure, hemorrhage, immune-mediated mechanisms and medullar hypoplasia." (PMID 32899831, 2020). "At post-QSP, one patient had anemia (<12 gr/ml) corrected with erythropoietin (Jehovah's witness), while eight others had their low levels of hemoglobin improved with iron (one intravenously and seven orally)." (PMID 32454830, 2020). "Recombinant human erythropoietin (rHuEPO) has been widely used in tumor patients with anemia, especially those receiving chemotherapy and radiotherapy." (PMID 32922549, 2020).